CAV1 (caveolin 1)
Diseases named in the same sentence as CAV1 in open-access papers (continued):
Sharing a sentence is not in itself a finding about the gene and the disease.
infection (continued). "In our study, we investigated the impact of Meth O on the expression of caveolin-1, clathrin heavy chain (CHC), and dynamin-2 in MDBK cells during early infection of BoHV-1." (PMID 39104584, 2024). "After infection of leptospires, the relative gene expression of ITGB1 in THP-1, ITGB1 and CAV-1 in HUVEC were up-regulated." (PMID 36137081, 2022). "Heat shock protein 70 (HSP70) and caveolin-1, which have been reported to enhance CSFV propagation, are revealed to be up-regulated during infection." (PMID 35129423, 2022). "Relative gene expression of ITGB1, ITGB2 ITGB3 and CAV-1 in THP-1 or HUVEC were analysed by comparing treatment of 4h leptospires infection and non-infection." (PMID 36137081, 2022). "This is supported by one of our previous studies, showing that the infection of neuronal cells with Ad-DHCR24-myc elevates cholesterol levels and is accompanied by an increase in caveolin 1 and insulin-like growth factor receptor." (PMID 32724824, 2020). "An early study has shown that co-expression of CAV-1 and HIV-1 is able to inhibit infection through the C-terminus hydrophobic transmembrane region of CAV-1, mainly by inhibiting the production of proviral DNA." (PMID 32357558, 2020). "Meanwhile, the cell membrane CAV-1 is significantly enhanced during the course of infection, suggesting that the invasion of CSFV Shimen into macrophages via a CAV-1-mediated pathway." (PMID 32357558, 2020). "Such stimulated Cav-1 expression is, therefore, one of the likely host factors that HIV modifies in its effort to establish a persistent infection." (PMID 28587148, 2017). "Overall, a trend of downregulation dominated the transcriptomic profile under infection, however, the genes C-X-C motif chemokine ligand 10 (CXCL10), IRG6 and CAV1 were upregulated for the majority of the comparisons." (PMID 28727780, 2017). "Cav-1 and NS3 colocalization appeared as early as 12 h post infection and increased until 24 h post infection." (PMID 24643062, 2014). "At 36 h post infection, there was a clear colocalization of the NS2B protein with Cav-1 and Flt-1 in a high percentage of cells, although the distribution varied slightly between cells." (PMID 24643062, 2014). "LR aggregates produced within A549 cell membranes after infection with H37Rv, HN878 and CDC1551 were quantified from confocal images for each MOI at 6 and 24 hpi using colocalization of CT-B and caveolin-1 as the marker for LR aggregation." (PMID 23024786, 2012). "Next, Cav-1RNAi-MDCK cells exhibiting the lowest Cav-1 levels (day 17 p.i.), wt-MDCK or RVH1Puro-MDCK were chosen for infection experiments with influenza A virus." (PMID 20504340, 2010). "In summary, our data in this manuscript supports that during the process of infection, HPV16 is subjected to partial proteolysis by cathepsins at the plasma membrane, in the endo-lysosome, or in the caveolin-1 positive vesicles." (PMID 19619315, 2009). "Intriguingly, infection efficiency of HPV16 PsVs was increased more than 50% when both clathrin and caveolin-1 mediated entry pathways were blocked." (PMID 18836553, 2008). "In addition, perturbation of Hrf-063 or eIF4A1 altered the expression of STAT1 and CAV1, and Hrf-063 regulated ISG15 and STING1 transcription in a time- and infection-dependent manner." (PMID 42306525, 2026). "Cell-to-cell spreading areas of infection was previously analyzed using HeLa caveolin-1 KD cells, but spreading was not eliminated, as approximately 30% of the area of infection on the coverslip monolayers remained." (PMID 40857412, 2025). "In contrast, when treating cells infected with E. coli, we did not observe any changes in the expression of caveolin-1, neither on the mRNA nor protein level compared with the infected, non-treated controls, indicating that infection treatment lacked effect." (PMID 41415272, 2025). "At 1 GFP infectious unit, nonsenescent WT cells had an approximately 90% infection rate, which was reduced to less than 50% following CAV1 KO." (PMID 39666389, 2024).
infection (continued). "Furthermore, the levels of p-Src, p-p38 MAPK, p-caveolin-1 Tyr14, and dynamin 2 in ARV-infected cells were further increased in cells which were pretreated with CSK inhibitor before infection for 2 h." (PMID 37097149, 2023). "Using double immunofluorescence staining, we found that a large amount of PCV3 virions colocalized with clathrin rather than caveolin-1 after infection." (PMID 33679671, 2021). "The results showed that neither nystatin nor caveolin-1 knockdown inhibited BPIV3 infection of HeLa cells, although nystatin effectively blocked cholera toxin (CTB) uptake." (PMID 34072688, 2021). "However, TLR2 showed reduced amounts of TLR2 in the cytoplasm of Cav1−/− MDSCs before BCG infection and a failure to increase intracellular TLR2 after infection." (PMID 31849990, 2019). "Meanwhile neither nystatin nor knocking down caveolin-1 (Cav1) in N2a cells had an effect on CVS-11 infection, suggesting that caveolae was independent for CVS-11 internalization." (PMID 31196105, 2019). "Quantification of antibody titre from cultured thymocytes isolated post-mortem from WT or Cav1 KO mice demonstrated a significant increase in worm antigen-specific IgG1, but a non-significant increase in IgG2c upon infection." (PMID 31189975, 2019). "The results showed that although the level of jam-a and caveolin-1 expression did not change significantly during the infection, the expression of ap2m1 and dynamin-2 in the various tissues exhibited significant changes." (PMID 30326628, 2018). "Cav-1 up-regulation by HIV infection and the observation that the overexpression of Cav-1 inhibits virus replication suggests that Cav-1 participates in maintaining a low-level persistent infection of macrophages in a feedback loop." (PMID 28587148, 2017). "At 12–14 hpi, the G protein formed relatively large punctate structures in the cell membrane, and no significant colocalization with caveolin-1 was detected at these early time points of infection." (PMID 28154158, 2017). "Vimentin knockdown abolished expression and recruitment of Vim and PSF to lipid raft fractions upon E44 infection, but did not change the pattern of caveolin-1." (PMID 27657497, 2016). "Immunoblotting of the membrane fractions of endosomes purified from the infected CHO-K1 cells after different periods of infection (5–120 min) revealed the simultaneous presence of ACT, Cav-1 (a major protein forming membrane caveolae), and Rab-5 (The same amount of protein was loaded in each case)." (PMID 26346097, 2015). "Notably, both inhibition of caveolar uptake and silencing of caveolar structure protein caveolin-1 resulted in increased HIV-1 integration and subsequent infection." (PMID 25551286, 2014). "In line with the known immunomodulatory effects of H. pylori, the expression of CD-markers related to T helper (CD4/GATA4) and regulatory T cells (CD25/FOXP3) was suppressed upon an 11-month infection with H. pylori SS1, and this phenomenon was most pronounced in Cav1-KO mice." (PMID 23592983, 2013). "In line with the selective recruitment of PI3K-p85 to Cav1 upon N927 infection, infection of AGS-Cav1 cells with N138 did not increase PI3K activity." (PMID 23717204, 2013). "In our study, we found that the tumor suppressor caveolin-1 (Cav1) is reduced upon infection with H. pylori, and CagA was sufficient but not necessary for this down-regulation." (PMID 23592983, 2013). "AGS clones with and without Cav1 were infected for 48 h with the cell-adapted CagA-delivery competent H. pylori strain G27 at different multiplicities of infection (MOI) ranging from 1∶100 to 1∶2000." (PMID 23592983, 2013). "By confocal microscopy performed at 30 min, 1 hr, and 24 hr post infection, viral entry, but not viral attachment, appeared markedly reduced in caveolin-1 -/- as compared to wild type mice at these time points." (PMID 24147000, 2013).
infection (continued). "The expression of endogenous Cav-1 was knocked down using specific siRNA, and the expression of Nef was accomplished by transfecting U87 cells with pCDNA3.1SF2Nef or pseudotyped HIV (psHIVwtNef) infection of THP-1 cell-differentiated macrophages." (PMID 23067370, 2012). "Conversely, increased expression of caveolin-1 in nonsenescent HeLa cells by infection with lentivirus carrying caveolin-1 led to an approximately 1.8-fold increase in entry by Salmonella." (PMID 20096033, 2010). "We found that the Cav-1 content decreased gradually to 25% of the value in wild-type MDCK at 14-17 days post infection (d.p.i.)(data not shown)." (PMID 20504340, 2010). "To ascertain whether ICAM-1 regulates the Src-Ezrin-Cav-1 pathway via Src to jointly regulate EMCV internalization, we initially analyzed the viral titers in both wild-type (WT) BHK-21 cell lines and ICAM-1 KO BHK-21 cell lines following EMCV infection." (PMID 40631914, 2025). "Unlike the invasion mechanisms of protozoans, during infection by the nematode A. cantonensis, an increase in Cav-1 expression in the brain and through the TLR4/MyD88 signaling pathway to activate MMP-9 leads to degradation of tight junction proteins (Zo-1 and claudin-5)." (PMID 38922036, 2024). "Our data provide insight into quite interesting nature of HAdV26 infection pathway suggesting that depending on the receptor status this virus can enter the cell in different manner which can be independent of dynamin-2, clathrin and/or caveolin-1." (PMID 35924932, 2022). "However, infection of Caco-2 cells by the control CVB3 Nancy strain, which is cholesterol- and caveola/lipid raft-dependent was inhibited by MβCD and nystatin, by depletion of caveolin-1 using siRNAs, and by the use of a DN mutant of caveolin-1." (PMID 30223898, 2018). "Moreover, the level of jam-a and caveolin-1 expression during the infection did not significantly differ between the two groups." (PMID 30326628, 2018). "Thus, we speculate that the caveolae-associated proteins incorporated into TFV virion might be obligated to participate in the interaction between caveolin-1 and TFV MCP at the late stage of infection." (PMID 26887868, 2016). "Because the strongest colocalization was observed between Cav-1 and NS3 by statistical Pearson analysis, we assessed whether the colocalization of NS3 and Cav-1 was a transient phenomenon that occurred late in infection." (PMID 24643062, 2014). "In addition, over-expression of Cav-1 by Ad-Cav-1 infection did not alter intracellular cholesterol inclusions in cells infected with psHIVΔNef." (PMID 23067370, 2012). "To confirm that chlamydial inclusions indeed could acquire caveolin-2 independently of caveolin-1, we further examined infections using caveolin-1 negative FRT cells." (PMID 15271223, 2004). "Our study found that within 30 min of infection with PEDV or PEAV, ALIX was enriched in CAV1 rather than Clathrin or RAB5." (PMID 38489378, 2024). "The results of western blot and gray scale analysis showed that BoHV-1 increased the expression of p-caveolin-1, CHC, and dynamin-2 at the initial infection stage, while not affecting the expression of caveolin-1, which was consistent with the report." (PMID 39104584, 2024). "The results indicated that chlorpromazine and knockdown of clathrin heavy chains (CHC) reduced CVS-11 infection, however, CVS-11 entry was not affected by nystatin or knockdown of caveolin-1." (PMID 31196105, 2019). "Surprisingly, while downregulation of CHC and Cav-1 had no drastic effects on the internalization of 22L and Chandler/RML PrPSc, it strongly affected the establishment of productive infection in L929 fibroblasts." (PMID 30970585, 2019). "Apart from IL-6 (miR-9 target), PIK3CA, and CAV1 (miR-124 target), no other target gene has been found to be reported previously either in a case of JEV infection or in infection by any other flaviviruses." (PMID 31578247, 2019).
infection (continued). "Consistent with a role for early and late endosomes and in contrast to the lack of effect of DN Eps15 and Cav-1 expression, GFP-tagged DN Rab5 or DN-Rab7 resulted in significant reduction (P<0.001 for each) in infection by gfpZEBOV." (PMID 20862315, 2010). "Also depletion of other proteins involved in caveolae-mediated endocytosis, including caveolin 1 (CAV1) and flotillins 1 and 2 (FLOT1 and FLOT2) did not affect MHV infection or fusion." (PMID 25375324, 2014). "Consistent with the results of these two studies, another study showed that the silencing of caveolin-1 in HepG2-NTCP cells did not decrease HBV infection, whereas the silencing of CHC, dynamin-2 (DNM2), and AP-2 resulted in a very large decrease in the level of infection." (PMID 32570893, 2020).
cardiovascular diseases (27 papers, 2010 to 2025). "Some population‐based studies have established the association between Cav‐1 and cardiovascular disease." (PMID 38757755, 2024). "There is consistent evidence describing the association between Cav-1 depletion and systemic cardiovascular disease, impaired autoregulation and defective NVC." (PMID 36760400, 2023). "We also show here that the loss of Cav-1 is protective against endothelial stiffening during ageing, the latter well-known to cause dysfunction and exacerbate the development of cardiovascular disease." (PMID 36280774, 2022). "Most of the published studies on Cav-1 and cardiovascular diseases employed Cav-1 deficient models, and researches on the mechanisms responsible for change in Cav-1 expression during these pathological processes are scarce." (PMID 24454806, 2014). "In cardiovascular diseases, Cav-1 deficiency often activates autophagy." (PMID 41030451, 2025). "Researches have found that in cardiovascular diseases, the targets regulated by Cav-1 and autophagy are mainly ECs and cardiomyocytes." (PMID 41030451, 2025). "Cav-1 is closely interlinked with endothelial nitric oxide synthase pathways that mediate vascular function and prevent cardiovascular diseases." (PMID 36760400, 2023). "Nor does the modest decrease in LDL cholesterol preclude intestinal epithelial CAV1 as a therapeutic target, as even a 1% reduction in LDL cholesterol leads to a 1% decrease in cardiovascular disease risk." (PMID 28130355, 2017). "Caveolin-1 elevation has been shown to contribute to the pathology of cardiovascular diseases, and caveolin-1 peptide was reported to be protective for the heart in myocardial I/R." (PMID 25629537, 2014). "Moreover, activation of some GPCRs would allow to control or to re-program Cav-1 expression levels to explore therapeutic outcomes in cardiovascular diseases." (PMID 33519523, 2020). "Furthermore, there is a physiologic relevant role of caveolin-1 in the effect of endothelial nitric oxide synthase activation and cardiovascular disease." (PMID 33224083, 2020). "Taken together, these results establish that caveolin-1 plays a central role in regulation of oxidative stress, metabolic switching, and autophagy in the endothelium, and may represent a critical target in cardiovascular diseases." (PMID 24498385, 2014). "Furthermore, the lack of Cav-1 improves NO-dependent vascular function and produces higher levels of NO, which suggests that Cav-1 impairs vascular function and contributes to the development of cardiovascular diseases." (PMID 33519523, 2020).
metabolic disease (22 papers, 2013 to 2025). A congenital disorder (due to inherited enzyme abnormality) or acquired (due to failure of a metabolically important organ) disorder resulting from an abnormal metabolic process. "One of these risk loci is the Caveolin-1 (CAV1) gene, its association with metabolic disorders has been demonstrated in animal models and human cohorts." (PMID 36338969, 2022). "The association between metabolic disease and CAV1 deficiency has been studied mainly in animal models." (PMID 34001235, 2021). "Due to limited studies on the CAV1 polymorphism, more researches are warranted to evaluate the impacts of insulin pathways on caveolin-related metabolic disease." (PMID 34001235, 2021). "It is remarkable that lipodystrophies with a defective local fat deposition that are seen in mutations of CAV1 gene indicate a new locus in the metabolic diseases." (PMID 34384444, 2021). "CAV-1 is also associated with oxidative stress, which can play a role in many metabolic diseases." (PMID 40628909, 2025). "Based on the present findings, it could be hypothesized that CAV1 (rs3807992) may be associated with increased metabolic disease risk factors in overweight and obese women." (PMID 34001235, 2021). "A probable role for CAV1 in metabolic diseases is shown by animal studies and has indicated that CAV1-deficient mice exhibit variations in lipid parameters including TC and HDL-C." (PMID 34001235, 2021). "This study presented the CAV1 gene as a possible genetic marker in recognizing people at higher risks for metabolic diseases." (PMID 34544501, 2021). "The CAV1 gene seems to be a genetic marker that might help in recognizing people at higher risks for metabolic diseases." (PMID 34544501, 2021). "Furthermore, it is widely acknowledged that the levels of caveolin-1, a major protein of caveolar structures, are increased in the organisms affected by metabolic diseases." (PMID 29385746, 2018). "Interestingly, apart from targeted SNP association studies, there has been no large-scale GWA study performed implicating CAV1 variants in the context of metabolic diseases in any ethnic group." (PMID 36338969, 2022). "The observed sexual dimorphism does not preclude intestinal epithelial CAV1 as a potential therapeutic target for metabolic disease as many pharmaceuticals currently in use have sexually dimorphic actions, including the LDL cholesterol-lowering drug fenofibrate." (PMID 28130355, 2017).